HMGB1 (high mobility group box 1)
Diseases named in the same sentence as HMGB1 in open-access papers (continued):
Sharing a sentence is not in itself a finding about the gene and the disease.
rheumatoid arthritis (continued). "Ethyl pyruvate (EP), a stable pyruvate derivate and certified inhibitor of an alarmin–high mobility group box 1 (HMGB1), exerts anti-oxidant and anti-inflammatory properties in animal models of rheumatoid arthritis and encephalomyelitis." (PMID 30687329, 2018). "In these bone-related inflammatory disorders, such as rheumatoid arthritis, amount of HMGB1 were released to the extracellular milieu." (PMID 26744383, 2016). "It has been demonstrated that HMGB1 plays an important role in the pathogenesis of several autoimmune diseases, including rheumatoid arthritis (RA), inflammatory bowel disease (IBD) and systemic lupus erythematosus (SLE)." (PMID 25884225, 2015). "In rheumatoid arthritis (RA), a positive proinflammatory feedback loop was found, where HMGB1 induces release of TNF-alpha from activated macrophages, which in turn induces translocation to the cytosol in macrophages." (PMID 26854151, 2015). "Matching results were reported from patients suffering from rheumatoid arthritis (RA): measurable amounts of extracellular HMGB1 were detected in synovial fluid of 14 out of 15 patients." (PMID 26854151, 2015). "The presence of cytoplasmic and extracellular HMGB1 has been reported in experimental arthritis models as well as in rheumatoid arthritis (RA) in humans." (PMID 23351605, 2013). "HMGB1 plays a role as a pro-inflammatory cytokine in rheumatoid arthritis and animal models of this disease." (PMID 20799933, 2010). "In addition, HMGB1 in its reduced form binds to CXCL12 via the chemokine receptor CXCR4 in rheumatoid arthritis (RA), and a high concentration of CXCL12/HMGB1 hybrid complex is dependent on the JAK/STAT pathway to maintain the inflammatory response." (PMID 38156383, 2023). "In addition, extracellular HMGB1 protein is a well‐known proinflammatory cytokine elevated in the synovial fluid of patients with rheumatoid arthritis and osteoarthritis." (PMID 33615102, 2021). "In rheumatoid arthritis HMGB1 has been shown to play a significant pathogenetic role." (PMID 23799067, 2013). "In the present study, we investigated the mRNA levels of HMGB1, RORγt, and IL-17 in peripheral blood mononuclear cells (PBMCs) from patients with rheumatoid arthritis by quantitative real-time PCR (RT-qPCR), and the concentrations of HMGB1, IL-17, and IL-23 in plasma were detected by ELISA." (PMID 22110531, 2012). "Moreover, RAGE activation by HMGB1 results in increased invasiveness of fibroblast-like synoviocytes from rheumatoid arthritis patients." (PMID 20799933, 2010). "Hence, HMGB1 is overexpressed in synovial tissue of rheumatoid arthritis patients and its extracellular form has been related to the progression of arthritis in animal models." (PMID 20799933, 2010). "Interestingly, HMGB1 potentiates Akt phosphorylation by IL-1β, a pathway involved in cell survival and proliferation of fibroblasts in rheumatoid arthritis synovium." (PMID 20799933, 2010). "We previously found that high-mobility group box protein 1 (HMGB1) promoted cell proliferation, migration, invasion, and autophagy in rheumatoid arthritis fibroblast-like synoviocytes (RA-FLS), but little is known about its regulatory mechanism." (PMID 31159863, 2019). "Extranuclear HMGB1expression was increased in the synovia of patients and animal models with rheumatoid arthritis (RA), and blockade of HMGB1 expression in experimental animal models can attenuate the RA." (PMID 30410469, 2018). "Extracellular HMGB1 acts as a proinflammatory mediator participating in the pathological processes of acute lung inflammation, transplant rejection, and ischemia-reperfusion injury in addition to rheumatoid diseases such as systemic lupus erythematosus, rheumatoid arthritis, and Sjogren's syndrome." (PMID 27800496, 2016). "HMGB1 has been described as a late inflammatory cytokine in several autoimmune diseases, such as rheumatoid arthritis (RA) and systemic lupus erythematosus (SLE)." (PMID 28018345, 2016).
rheumatoid arthritis (continued). "Synovial fibroblasts obtained from rheumatoid arthritis (RA) and osteoarthritis (OA) patients were stimulated with HMGB1 alone or in complex with LPS, IL-1α or IL-1β." (PMID 21871094, 2011). "We and others have demonstrated an extracellular expression of HMGB1 in synovial tissue biopsies from rheumatoid arthritis (RA) patients and in joints from mice and rats with adjuvant-induced arthritis or collagen type II-induced arthritis." (PMID 21871094, 2011). "The aim of this study was to determine whether HMGB1 in complex with LPS, interleukin (IL)-1α or IL-1β has enhancing effects on the production of proinflammatory mediators by rheumatoid arthritis synovial fibroblasts (RASF) and osteoarthritis synovial fibroblasts (OASF)." (PMID 21871094, 2011). "Extracellular HMGB1 may act as a pro-inflammatory cytokine in rheumatoid arthritis." (PMID 20799933, 2010). "It is known that pro-inflammatory cytokines such as IL-1β or TNFα stimulate HMGB1 translocation into the cytoplasm and release in different cell types, although TNFα is not the main inducer of extracellular HMGB1 during synovitis in rheumatoid arthritis patients." (PMID 20799933, 2010). "Additionally, in animal models comparing rheumatoid arthritis with osteoarthritis significantly higher levels of HMGB1 were found in synovial fluid in the context of RA." (PMID 37048161, 2023). "These are consistent with a previous study where HMGB1 induced the expression of HIF-1α and angiogenesis in rheumatoid arthritis." (PMID 35586052, 2022). "As a natural alarmin, HMGB1 is involved in the inflammatory response of acute local organ injury, as well as Th17-mediated autoimmune diseases, such as rheumatoid arthritis (RA), multiple sclerosis (MS), and its animal model-experimental autoimmune encephalomyelitis (EAE)." (PMID 33344656, 2020). "Early reports have demonstrated that antibodies to HMGB1 and HMGB2 are found in about 1/3 of SSc Sera and anti-HMGB1/HMGB2 antibodies are detected commonly in systemic rheumatic diseases, particularly in rheumatoid arthritis and SSc." (PMID 25284457, 2014). "It was, therefore, decided to investigate whether treatment based on TNF blockade in rheumatoid arthritis (RA) affects the expression of synovial HMGB1." (PMID 18346273, 2008). "Recently, high-mobility group box chromosomal protein 1 (HMGB1), a nonhistone nuclear DNA-binding protein, is proved to be a potent proinflammatory mediator in rheumatoid arthritis." (PMID 22110531, 2012). "HMGB1 is involved in various diseases without obvious infections; for example, rheumatoid arthritis, hemorrhagic shock, cerebral and myocardial ischemia, acute lung injury, and acute pancreatitis." (PMID 21989210, 2011). "Furthermore, HMGB1 can be released into the extracellular environment, where it acts as a DAMP molecule, contributing to pro-inflammatory immune responses and disease progression in conditions such as systemic lupus erythematosus and rheumatoid arthritis." (PMID 39693295, 2024). "In addition, a wide range of endogenous TLR activators, such as heat shock protein and HMGB1, have been observed in the synovium of patients with rheumatoid arthritis (RA) but not in the non-inflammatory synovium of patients with normal joints or osteoarthritis (OA)." (PMID 36674552, 2023).
epilepsy (105 papers, 2011 to 2025). A brain disorder characterized by episodes of abnormally increased neuronal discharge resulting in transient episodes of sensory or motor neurological dysfunction, or psychic dysfunction. "In murine models of acute pancreatitis, PFD treatment resulted in reduced serum levels of HMGB1 and C-reactive protein, two inflammatory markers that have been linked to poor outcomes in clinical studies of epilepsy." (PMID 39911825, 2024). "It is evident that HMGB1, like caspase-3, can mediate neuronal apoptosis-associated epilepsy by affecting mitochondrial structure and function." (PMID 39876842, 2024). "Activation of the HMGB1‐associated pathway is evident in surgically resected brain tissues from epilepsy patients." (PMID 39046369, 2024). "HMGB1 is an inflammatory marker widely associated with epilepsy; however, currently, there is a paucity of evidence showing a correlation between central and peripheral HMGB1 levels." (PMID 37239204, 2023). "HMGB1 can enhance seizures induced by heat treatment in developing rats and secondary epilepsy associated with seizures induced by long-term heat treatment." (PMID 36869074, 2023). "Of interest is the unique potential of this protein, HMGB1, as a treatment and non-invasive biomarker for epilepsy and patients at high risk of developing epilepsy." (PMID 37239204, 2023). "Studies conducted on rats have also strongly linked HMGB1 with the impaired cognitive abilities associated with neuroinflammation and epilepsy." (PMID 33921725, 2021). "Changes in the levels of HMGB1 in the brain are mirrored in blood, so measuring blood levels of HMGB1 in patients can predict with high accuracy the risk of developing epilepsy." (PMID 32521797, 2020). "Further investigations were carried out on 19 out of 28 epileptic dogs to identify changes in serum HMGB1 concentration after the treatment of underlying brain disease and epilepsy." (PMID 33150666, 2020). "In the CNS, HMGB1 has been implicated in cerebral edema, neurodegeneration and neuroinflammation in a range of injury paradigms and disease states, including epilepsy and TBI." (PMID 31717556, 2019). "The TLR-4 and RAGE inflammatory pathway is stimulated by one of the most important pro-inflammatory cytokines knows as HMGB1, which is responsible for the release of glutamate and causing hyperexcitability of the brain during epilepsy." (PMID 31057394, 2019). "HMGB1 acts as a pathogenic inflammatory response to mediate ranges of conditions such as epilepsy, septic shock, ischemia, TBI, PD, AD, and MS." (PMID 30271319, 2018). "Our results, together with those from other studies, suggest that HMGB1 activation is an important feature associated with epilepsy and febrile seizures." (PMID 21989210, 2011). "Concentrations of HMGB1 are also correlated with increased risk and severity of epilepsy in adults." (PMID 41155637, 2025). "Mitochondrial dysfunction can induce epileptogenesis by mediating multiple programmed cell deaths in neurons, and HMGB1 may intervene in epilepsy-associated multiple programmed cell deaths by modulating mitochondrial function." (PMID 39876842, 2024). "HMGB1, which is secreted extracellularly, may drive the disease process in epilepsy by inducing neuroinflammation and neuronal loss during the silent phase following the initial triggering event." (PMID 39876842, 2024). "An increased level of HMGB1 induces inflammation, which may lead to additional complications associated with epilepsy." (PMID 37239204, 2023). "DAMPs, particularly HMGB1, have been implicated in epilepsy pathogenesis." (PMID 36035987, 2022). "Several studies have reported elevated HMGB1 levels in the serum/plasma/CSF and brains of epileptic patients or animal seizure models, correlating with higher risk and severity of epilepsy." (PMID 34830412, 2021).
epilepsy (continued). "HMGB1 contributes to the onset of FS and plays an important role in the occurrence of secondary epilepsy associated with the prolongation of FS,104 and the occurrence of adult epilepsy is related to the recurrence of FS in childhood." (PMID 33140586, 2021). "Taking our results into consideration, serum HMGB1 could be a biomarker of epilepsy or it might be associated with epileptogenesis in epileptic dogs, like in human patients with epilepsy." (PMID 33150666, 2020). "Although there have been no reports on changes in serum HMGB1 concentrations with the administration of antiepileptic drugs, it has been reported that seizure frequency is associated with elevated serum HMGB1 concentration at the initial visit in human patients with epilepsy." (PMID 33150666, 2020). "HMGB1 displayed a good predictive value of epilepsy risk with an AUC of 0.905 (95%CI, 0.864−0.946)." (PMID 31241711, 2019). "One hundred and five epilepsy patients and 100 healthy controls (HCs) were enrolled in this case-control study, and serum samples were collected from all participants to assess the HMGB1 and TLR4 expressions by enzyme-linked immunosorbent assay (ELISA)." (PMID 31241711, 2019). "While the brain regions and neural circuits underlying addiction and epilepsy differ, stress and drug abuse may share a common mechanism of neurocircuitry sensitization through increased HMGB1 and TLR signaling." (PMID 28210782, 2017). "The disulfide isoform of HMGB1, which seems to be the form most likely to promote seizure generation, is a potentially novel prognostic, diagnostic, and predictive biomarker of drug-resistant epilepsy in humans and highlights potential new targets for drug development." (PMID 35837232, 2022). "However, it was found that the epilepsy course may be associated with elevation of serum HMGB1 level in dogs with IE." (PMID 33150666, 2020). "HMGB1 has been additionally indicated as a potential therapeutic agent in epilepsy and as a non-invasive biomarker, which could identify patients with high risk of epilepsy." (PMID 31312171, 2019). "Nuclear factor kappa-light-chain-enhancer of activated B cells (NF-κB) and high-mobility Group box 1 (HMGB1) are the primary mediators of neuroinflammation that are involved in epilepsy pathogenesis." (PMID 40642386, 2025). "During intervals of seizures, increased levels of HMGB1 were also detected in the serum of patients with epilepsy." (PMID 41155637, 2025). "In line with our findings, several investigations found that epilepsy patients had greater HMGB1 concentrations than the control group, and as an independent risk factor for epilepsy prognosis." (PMID 39466324, 2025). "Patients with epilepsy demonstrated increased levels of HMGB1 (by nearly 80%) in the serum after generalized convulsive seizures." (PMID 41155637, 2025). "Elevated blood levels of HMGB1 have been measured in patients with drug-resistant compared to drug-sensitive epilepsy and healthy controls." (PMID 41356251, 2025). "We aimed to investigate circulating HMGB1 in children with epilepsy and its connection to cognitive function and drug responsiveness." (PMID 39466324, 2025). "For example, in epilepsy, damaged or stressed cells, such as neurons and glial cells, release the damage-associated molecular pattern (DAMP) HMGB1." (PMID 40941042, 2025). "High Mobility Group Box1 (HMGB1) is an activator of neuroinflammation, and it is possibly involved in the initiation and progression of epilepsy." (PMID 39466324, 2025). "Although the role of lactylation in epilepsy is underexplored, the lactylation of proteins like HMGB1, a biomarker in epilepsy, suggests its relevance in epileptogenesis." (PMID 39904962, 2025). "The current review highlights the roles of the IL-1/IL-1R1/IL-1Ra pathway and HMGB1/TLR4 pathway as crucial mechanisms underlying epileptogenesis and sustaining epilepsy, making them potential therapeutic targets." (PMID 41155637, 2025).
epilepsy (continued). "Neuroinflammation, a key contributor to epilepsy pathogenesis, was evident via elevated NF-κB levels and induced HMGB1 expression." (PMID 40642386, 2025). "Regarding the role of TLR4 and NF-κB in epilepsy, previous studies have demonstrated that the overexpression of HMGB1, which signals through TLR4 and activates NF-κB, exacerbates epileptogenesis." (PMID 40718441, 2025). "In particular, HMGB1 is a key mediator of neuroinflammation involved in epileptogenesis in animal models of acquired epilepsy." (PMID 41356251, 2025). "The subgroup analysis conducted on specimen types indicates that people diagnosed with epilepsy have increased levels of plasma high‐mobility group box‐1 (HMGB1) and cerebral spinal fluid HMGB1 in comparison to the control group." (PMID 40103702, 2025). "Elevated HMGB1 levels, especially in patients with drug-resistant epilepsy, correlate negatively with cognitive performance, emphasizing its importance as a potential marker for early prediction of drug resistance and impairment of cognitive function." (PMID 39466324, 2025). "Anti-HMGB1 monoclonal antibody exhibits antiseizure effects in both mouse and zebrafish models of epilepsy and can improve epilepsy-related memory impairment." (PMID 41155637, 2025). "Some studies have documented the use of HMGB1 as a biomarker for epilepsy, which can be used to assess illness progression and has also proven to diagnose DRE." (PMID 39466324, 2025). "Glycyrrhizin exerts neuroprotective and anticonvulsant effects in epilepsy by regulating pyroptosis via the HMGB1/TLR4/NF-κB signaling pathway, offering novel insights into its potential as a DMT for epilepsy." (PMID 39834818, 2024). "High mobility group box 1 (HMGB1), which is also an inflammatory protein, attracts attention in epilepsy studies conducted with animal models." (PMID 39046369, 2024). "HMGB1, serving as a biomarker for epilepsy, plays a crucial role in initiating neuroinflammation following epileptogenic injury." (PMID 39206290, 2024). "Encouragingly, antagonists targeting the HMGB1/TLR4 pathway have shown promise in mitigating epilepsy-related pathology." (PMID 38792602, 2024). "Recent research has shown that HMGB1 is expressed at markedly elevated levels in the bloodstream of individuals with drug-resistant epilepsy compared to those with well-managed seizures and healthy individuals." (PMID 39206290, 2024). "A clinical study suggested that increased HMGB1 or TLR4 expression is associated with a higher risk and severity of epilepsy, as well as an increased likelihood of anticonvulsant drug resistance." (PMID 39046369, 2024). "HMGB1 is mainly involved in the epilepsy pathophysiology by interacting with the primary receptor TLR4." (PMID 39046369, 2024). "In parallel with the literature, HMGB1 expression was also higher in the epilepsy group in our study." (PMID 39046369, 2024). "Based on these results, we can state that epilepsy and T. gondii use different proteins in the HMGB1/RAGE/TLR4/NF‐κB signalling pathway." (PMID 39046369, 2024). "In the literature, HMGB1 has been found to be elevated in brain tissue and cerebrospinal fluid (CSF) samples obtained after epilepsy surgery, as in our study." (PMID 39046369, 2024). "These anti-inflammatory effects, including the reduction of cytokine production and HMGB1 release, align with observations from different brain injuries induced by ischemia/reperfusion, hemorrhage, trauma, and epilepsy in various studies." (PMID 38892076, 2024). "HMGB1 levels were found to be higher in the blood of animals with active epilepsy compared to healthy subjects or controls." (PMID 39046369, 2024). "HMGB1 is thought to be involved in the ictogenesis of epileptic insults, and anti-HMGB1 treatment seems to be beneficial for forms of epilepsy in several animal models." (PMID 37048161, 2023). "Another mechanism of extracellular HMGB1 contributing to epilepsy is based on the destruction of the BBB." (PMID 38187384, 2023).